HDAC6 (histone deacetylase 6)
Diseases named in the same sentence as HDAC6 in open-access papers (continued):
Sharing a sentence is not in itself a finding about the gene and the disease.
tumor (320 papers, 2007 to 2026). "As a consequence, patients, whose tumour intensively expressed HDAC6 showed a 3.248-fold increase mortality risk compared with the low HDAC6 expression group (P=0.003,)." (PMID 40535577, 2025). "The requirement for HDAC6 expression in malignant cell growth was confirmed when HDAC6-null mice and HDAC6-deficient fibroblasts were shown to be more resistant to tumour formation." (PMID 39941046, 2025). "They found that ciliary reduction in this neoplasia appeared to be linked to the overexpression of histone deacetylase 6 (HDAC6), an enzyme that deacetylates tubulin in the PC axoneme, thereby inducing their resorption." (PMID 41196390, 2025). "ARID1A loss impairs interferon signaling, facilitating immune evasion, and is associated with increased expression of HDAC6, which promotes tumor cell invasion, migration, and poorer overall survival." (PMID 41383608, 2025). "Lower HDAC6 expression in MLNs compared to primary tumours is considered an independent prognostic marker associated with better survival rate for oesophageal cancer patients." (PMID 39941046, 2025). "The three class II HDACs (HDAC4, HDAC5, HDAC6) exhibited similar expression patterns, with predominantly cytoplasmic staining, that was higher in epithelial rich TETs (B3, C) and more advanced tumor stages, while it was also associated with disease recurrence." (PMID 36901692, 2023). "Meanwhile, proteasome activity has been linked to tumor metastasis, and therapy based on inhibiting the proteasome and HDAC6 has been proposed as an underlying strategy for OC treatment." (PMID 35281472, 2022). "miR-22-overexpressing macrophages inhibited glioma formation by targeting HDAC6 and NF-κB signaling in tumor-associated macrophages (TAMs)." (PMID 36076996, 2022). "By combining RNA sequencing (RNA-seq) with ChIP-seq for active histone mark H3K27ac, we observed that a reduction in H3K27ac enrichment on HDAC6 promoter regions was associated with a reduction in HDAC6 gene expression in LIPG knockdown tumor cells." (PMID 35954428, 2022). "Our study found that HDAC6 expression was significantly associated with the tumor grade and mortality risk in OSCC." (PMID 35732647, 2022). "HDAC-1 nuclear expression was associated with increased tumor size (p = 0.03), HDAC-6 with higher mitotic index (p = 0.03), and nuclear HDAC-2 with epithelioid cell morphology (p = 0.03) and presence of tumor-infiltrating lymphocytes (p = 0.04)." (PMID 34638249, 2021). "HDAC-1 was associated with increased tumor size, HDAC-6 with mitotic index, and HDAC-2 with epithelioid cell morphology, presence of ILS, and gain of chromosome 8q, all parameters of adverse prognosis." (PMID 34638249, 2021). "Abnormal expression of HDAC6 was associated with immune checkpoints, immune cell infiltration, tumor microenvironment, TMB, MSI, and DNA methylation." (PMID 34485153, 2021). "There is upregulated HDAC6 expression in numerous types of tumor tissues and is closely associated with clinicopathological characteristics." (PMID 34938729, 2021). "Secondly, through this experiment, we confirmed that HDAC6 expression level was associated with tumor immune infiltration and tumor microenvironment, especially in PAAD." (PMID 34485153, 2021). "Phthalates also are suspected to cause the proliferation and metastasis of BC cells and tumor progression via up-regulating histone deacetylase 6 (HDAC6)." (PMID 33203443, 2020). "HDAC6 inhibitors are promising candidates for the treatment of neurological diseases, neoplasms, infectious diseases, and other diseases associated with HDAC6 activity." (PMID 31354911, 2019). "In tumor xenoplant assays, HDAC6 deficiency or small molecule inhibition by the selective HDAC6 inhibitors tubacin or tubastatin A was found to significantly impede tumor growth." (PMID 29423038, 2018). "HDAC6 has been shown to modulate the expression of specific tumor-associated antigens, MHC class I proteins, co-stimulatory molecules and cytokine production." (PMID 30176876, 2018).
tumor (continued). "Despite their inability to impact the proliferation or viability of FGFR3K644E plus MYC transformed MEFs, both tubastatin A and HDAC6 deficiency did significantly reduce tumor growth by these cells." (PMID 29423038, 2018). "The best example is HDAC6, which has been implicated in regulation of microtubules, growth factor-induced chemotaxis, misfolded protein stress response and tumor invasion." (PMID 26848526, 2016). "Enhanced HDAC-6 expression was significantly associated with earlier histopathological stage (p = 0.0115) and borderline with smaller tumor size (p = 0.0864)." (PMID 26502922, 2015). "Treatment of tumor cells with pan HDACis has been reported to cause acetylation of Hsp90 through inhibition of HDAC6 and depletion of several Hsp90 client proteins including AKT and c-RAF." (PMID 21179472, 2010). "Moreover, the phenotypic responses associated with ricolinostat in tumours have been reported at concentrations higher than the HDAC6-selective concentrations in which the reported toxicity of IC50 doses were found to be high enough to inhibit nuclear HDACs." (PMID 39941046, 2025). "Furthermore, the loss of HDAC6 caused tumour cells to be less responsive to the oncogenic RAS pathway and activation of its signalling cascade." (PMID 39941046, 2025). "However, taken together, our data demonstrate that the anti-tumor effects of Compound 10 are closely associated with its ability to inhibit HDAC6 enzymatic activity, resulting in enhanced acetylation of downstream substrates." (PMID 41011174, 2025). "HDAC6 inhibitors can inhibit the function of tumor-associated macrophages and myeloid-derived suppressor cells in the tumor microenvironment, and promote the activity of cytotoxic T cells and memory T cells and their killing effect on tumor cells." (PMID 38231305, 2024). "In addition, overexpression of HDAC6 is associated with advanced tumor stage and increased tumor invasiveness, with a lower survival period." (PMID 38988323, 2024). "The use of HDAC6 inhibitors could represent a therapeutic strategy for patients diagnosed with advanced stages of ARID1A‐mutated tumours." (PMID 35167193, 2022). "It suggested that there was an association between HDAC6 and tumor prognosis, especially with THYM." (PMID 34485153, 2021). "Additionally, HDAC-1 was associated with increased tumor size, HDAC-6 with mitotic index, and HDAC-2 with epithelioid cell morphology and presence of tumor-infiltrating lymphocytes, both parameters of adverse prognosis." (PMID 34638249, 2021). "Utilizing Arid1a-mutated OCCC mice treated with the HDAC6 inhibitor and anti-PD-L1 immune checkpoint blockade, they further found that tumor burden reduced and mice survival improved because of the activation and increased presence of interferon-gamma-positive CD8 T cells." (PMID 34671561, 2021). "However, according to The Cancer Genome Atlas (TCGA) data-set, 4% of patients with ccRCC show upregulation of HDAC-1 and HDAC-6 mRNA and direct association with an advanced tumor stage in a, nevertheless, insignificant manner." (PMID 34441281, 2021). "Thus, it is probable that MM is a specific neoplasm susceptible to proteasome-, autophagy- and histone deacetylase 6 (HDAC6)-inhibitors." (PMID 33014130, 2020). "High expression of HDAC6 was proposed to be linked with tumor aggressiveness." (PMID 33322608, 2020). "Thus, MM is originally a fragile neoplasm particularly susceptible to autophagy-, proteasome- and histone deacetylase 6-inhibitors." (PMID 33014130, 2020). "Thus, MM is a specific neoplasm particularly susceptible to proteasome, autophagy and HDAC6 inhibitors." (PMID 33014130, 2020). "Additionally, we identified an increased infiltration of CD8 and natural killers (NK) cells, and a diminished presence of pro-tumoral M2 macrophages in the tumor microenvironment (TME) associated with HDAC6 treatment." (PMID 30992475, 2019). "However, tubacin was more effective at inhibiting tumor growth than tubastatin A or HDAC6 deficiency." (PMID 29423038, 2018).
tumor (continued). "Here, we show that FGFR3-dependent tumors are sensitive to tubacin, tubastatin A and HDAC6 deficiency and reveal unique, HDAC6-independent activities of tubacin that may contribute to its superior ability to block tumor growth." (PMID 29423038, 2018). "We have shown that tumour types, with high protein turnover in general could be more susceptible to therapy with HDAC6 inhibitors." (PMID 30318510, 2018). "Furthermore, combination of HDAC6 inhibitor with a PI3K inhibitor caused substantial tumor growth inhibition in vivo compared with either treatment alone, also detectable by Ki-67 immunostaining and 18F-FLT positron emission tomography (PET)." (PMID 27362804, 2016). "Therefore, HDAC6 inhibition selectively promoted apoptosis of cells with ARID1A mutation, but not ARID1A wildtype, as verified by the improved survival of ARID1A-deficient tumor-bearing mice upon treatment of a clinically applicable small molecule inhibitor of HDAC6." (PMID 36980292, 2023). "Thus, tumour suppressive functions of RanBPM may be at least in part linked to its ability to repress the oncogenic effects of HDAC6 activity." (PMID 24795145, 2014). "The overexpression of HDAC1, HDAC2, HDAC3, and HDAC6, together with aberrant DNA methylation, contributes to tumor suppressor gene silencing." (PMID 41562705, 2026). "Global proteome and secretome profiling of HDAC6-knockout (KO) cells revealed upregulation of several immune-related modulators, including RNase T2, a tumor suppressor known to modulate the tumor microenvironment." (PMID 41794832, 2026). "The upregulation of ONECUT3 in CRC facilitates tumor growth by enhancing the transcriptional activity of HIF-1α through HDAC6-mediated deacetylation." (PMID 40032849, 2025). "Overexpression of HDAC6 has been reported in various tumour types, making it a promising target for anticancer therapy." (PMID 39941046, 2025). "By deacetylating α-tubulin, HDAC6 plays a critical role in the growth, progression, and migration of tumor cells through regulating cytoskeletal dynamics." (PMID 41249257, 2025). "Together, these results identify HDAC6 inhibition as a regulator of endogenous FH activity in tumour cells, and highlight it as a promising candidate for indirectly targeting tumour metabolism." (PMID 40721560, 2025). "Among the Zinc-dependent HDAC, HDAC6 is a peculiar enzyme with a recognized involvement in tumor growth and development and in the modulation of the immune functions." (PMID 40433358, 2025). "Although others have previously shown that selective HDAC6 inhibition produces anti-tumor effects synergistically augmented by bortezomib, a precise mechanism has not been described." (PMID 41458974, 2025). "It has been recently shown that selective HDAC6 inhibition suppresses tumor growth and restores sensitivity to chemotherapeutics or antitumor agents." (PMID 41458974, 2025). "Utilising stochastic optical reconstruction microscopy (STORM), we pinpoint the sites of interaction to the mitochondria, thereby demonstrating a regulation of FH activity in tumour cells following HDAC6 inhibition." (PMID 40721560, 2025). "In this context, HDAC6 selective inhibitors have proven efficacy in downregulating PD-L1 expression both on certain types of tumor cells and myeloid cells, such as DCs and macrophages." (PMID 40433358, 2025).
tumor (continued). "Intriguingly, HDAC6 has been demonstrated to regulate fat-induced lipid storage and to be inhibited by fatty acid supply in tumor cells." (PMID 41458974, 2025). "After confirming the ability of Compound 10 to enzymatically inhibit HDAC6, we exploited MM as a model to investigate its anti-tumor activity." (PMID 41011174, 2025). "Nonetheless, discerning which tumours to treat will inevitably help stratify patients best suited to HDAC6 inhibitory therapy and improve the success of this class of drugs in the clinic." (PMID 39941046, 2025). "By inhibiting HDAC6, Vorinostat reduces IL-10 levels, which decreases M2 macrophage polarization and consequently limits tumor growth." (PMID 40330466, 2025). "Here, we report a regulation of fumarate hydratase (FH) activity in tumour cells that is mediated by the lysine deacetylase, HDAC6." (PMID 40721560, 2025). "Altogether, these data illustrate a unique regulation of FH activity in mitochondria of tumour cells by HDAC6 inhibition and that disruption leads to fumarate accumulation, protein succination, and mtROS-dependent cell death." (PMID 40721560, 2025). "Given the complexity of the OCCC TME, therapeutic strategies that combine ICIs with agents targeting key molecules implicated in tumor aggressiveness such as VEGF, HIF-1α, IL-6, IL-10, PI3K, and HDAC6 show considerable promise." (PMID 41383608, 2025). "The analysis of 33 tumours using multiple data sources from The Cancer Genome Atlas (TCGA) and the NCI-60 drug screening database revealed that most tumours exhibited lower levels of HDAC6 and HDAC10 compared to normal tissues." (PMID 39941046, 2025). "It has been shown that HDAC6 promotes the occurrence and development of tumors by affecting tumor immunogenicity and immune cell activity." (PMID 38231305, 2024). "We also demonstrated that HDAC6 inhibition in macrophages suppressed the polarization toward tumor-promoting phenotype by attenuating STAT3-mediated M2 reprogramming." (PMID 39272209, 2024). "In SCLC xenograft mice, JQ1 and the histone deacetylase 6 (HDAC6) inhibitor ACY-1215 combined to exert anti-tumor activity dependent on the presence of NK cells." (PMID 38681203, 2024). "We previously reported that a functional immune system is required for HDAC6 inhibition-mediated tumor suppression using immunodeficient SCID mice and CD4/CD8 T-cell depletion assays." (PMID 39272209, 2024). "To investigate the potential anti-tumor activity of the four compounds that displayed HDAC6-inhibitory activity, we tested their antiproliferative ability in LNCaP and PC-3 cells." (PMID 39204176, 2024). "When the 4-chlorophenyl moiety is substituted by pyridine or other phenyl groups, the selectivity for HDAC6 increases, together with the anti-tumour properties." (PMID 39595195, 2024). "In the LinkedOmics database, CBX2, NOTCH3, HDAC6 and HDAC11 were linked with tumor purity and TNM stage." (PMID 38702698, 2024). "WT161 is a recently developed HDAC6 inhibitor that has recently been used primarily in tumour therapy trials." (PMID 38245771, 2024). "The HDAC inhibitor SAHA has been found to decrease HIF1α levels in tumor cell lines via direct acetylation of heat shock protein 90 (Hip90), a HIFα chaperone protein, using HDAC6." (PMID 38279330, 2024). "HDAC6 is involved in the regulation of tumor cell proliferation, apoptosis, migration and invasion, autophagy, DNA damage response and immune regulation." (PMID 38231305, 2024). "Overall, HDAC6 inhibition in ACT macrophages significantly reduced tumor volume through antitumor M1 macrophages and increased infiltration of CD8 effector T-cells." (PMID 39272209, 2024).
tumor (continued). "HDAC6 inhibitors not only exert direct anti-tumor effects but also hold promise for synergistic effects and overcoming drug resistance when used in combination with other therapeutic modalities." (PMID 39063958, 2024). "Previous studies have shown that HDAC6 can participate in the immunomodulatory process of tumor occurrence and development by up-regulating the expression of PD-L1." (PMID 38231305, 2024). "On the other hand, class IIA and IIB HDACs (HDAC4/5/7/9 and HDAC6/10, respectively) exhibit both up- and downregulation in tumors depending on the tumor type." (PMID 39063083, 2024). "Studies have shown that HDAC6 selective inhibitors have the additive effect in tumor therapy when used in combination with other anti-tumor drugs." (PMID 38231305, 2024). "Inhibition has been shown to exert an anti-tumor effect, however, only in immunocompetent mice, suggesting that the anti-tumor activity of HDAC6 inhibitors (HDAC6i) requires an intact adaptive immune system." (PMID 38533720, 2024). "The study found a significant upregulation of HDAC6 mRNA expression in RCC tissues compared to adjacent non-tumor tissues." (PMID 39063958, 2024). "HDAC6 inhibitors can also transform Treg cells and M2 macrophages, thereby increasing the number of cytotoxic T cells and M1 macrophages to reshape the tumor immune microenvironment." (PMID 38231305, 2024). "Simultaneously, in the context of disruptions in Ras, mTOR, and histone deacetylase 6 (HDAC6), among others, SGs can promote tumor signaling by enhancing translation and the assembly of core components of protein–protein interactions within the SG structure." (PMID 38383403, 2024). "Until recently, most research on HDAC PROTACs was focused on hematological malignancies that are more sensitive to HDAC6 degraders regarding degradation of HDAC6 although some encouraging results were observed in tumor cell lines derived from solid tumors." (PMID 38258065, 2023). "In a mouse model of colon cancer, the HDAC6 inhibitor was used in combination with bortezomib to inhibit tumor growth in vivo." (PMID 37666811, 2023). "Experimental data obtained on HDAC6 inhibition in combination with immunotherapeutic agents in the settings of tumor cell lines and animal models have shown an improved antitumor effect of this drug combination compared to each agent alone." (PMID 38258065, 2023). "It was reported that the deacetylation of LC3-II by HDAC6 promotes its translocation to the cytoplasm and autophagy, thereby inducing the survival of nutrient-deprived tumor cells." (PMID 38258065, 2023). "HDAC6 regulates signaling pathways that are involved in tumor cell growth, survival, and invasiveness and are often overexpressed in the majority of malignancies, including CRC." (PMID 38258065, 2023). "Due to its ability to remove misfolded proteins, induce autophagy, and regulate unfolded protein response, HDAC6 plays a protective role in responses to stress and enables tumor cell survival." (PMID 38258065, 2023). "HDAC6 deregulation is a significant contributing factor to tumor development due to its involvement in regulating multiple cellular processes." (PMID 37345170, 2023). "PRDX1, by modulating the HEF1/Aurora A/HDAC6 signaling pathway, fosters the loss of primary cilia, contributing to ESCC tumorigenesis and tumor growth." (PMID 37781072, 2023). "In conclusion, both in vitro and in vivo studies strongly suggest that JBI-097 acts via the simultaneous inhibition of the LSD1 and HDAC6 pathways, to inhibit proliferation, enhance differentiation, and consequent tumor inhibition." (PMID 36595522, 2023). "To validate, we focused on HDAC6 for further analysis, and found a significantly high impact on the viability of tumor cells when HDAC6 inhibitor (ACY1215) was combined with the meticrane." (PMID 37274234, 2023). "Here, we evaluated JBI-097 a dual LSD1/HDAC6 inhibitor, for its in vitro and in vivo activities in various tumor models." (PMID 36595522, 2023).